SRI (sorcin)
Diseases named in the same sentence as SRI in open-access papers (continued):
Sharing a sentence is not in itself a finding about the gene and the disease.
cancer (continued). "Beyond its role in cancer, Sorcin is overexpressed in brain tissue from Alzheimer’s and Parkinson’s patients, where it may counteract the elevated cytosolic calcium (Ca2+) concentrations associated with neurodegeneration by facilitating Ca2+ uptake into the endoplasmic reticulum." (PMID 41133884, 2025). "Mass spectrometry analysis and database searching have revealed that sorcin is widely expressed in most human tissues, such as skeletal muscle, kidney, brain, cardiac muscle, breast and skin, and it is overexpressed in a variety of human tumors and human cancer cell lines." (PMID 34205207, 2021). "Further validation in four independent cohorts showed that KEAP1, SRI, MFAP1, MFAP2, INCENP, and KIF21B were consistently upregulated in cancer tissues, while MYOZ3, DST, and TIAM1 were consistently downregulated." (PMID 40228435, 2025). "Heatmap results showed that NRP1, MFAP2, KLC1, DST, and MYOZ3 were generally downregulated in cancer cell lines, while KIF21B, SRI, INCENP, and KEAP1 were also downregulated." (PMID 40228435, 2025). "Sorcin can be considered an oncogene and a marker of multidrug resistance (MDR), since its overexpression confers MDR in cancer cell line models, while its silencing increases sensitivity to chemotherapeutic drugs." (PMID 37442828, 2023). "We applied the TIMER2 approach to analyze the expression status of ANXA7 and SRI in a panel of human cancers using the TCGA database and found the relative overexpression of ANXA7 and SRI in most human cancers." (PMID 34716295, 2021). "Sorcin (SRI), a soluble resistance-related calcium-binding protein, has been reported to be an oncogenic protein in cancer." (PMID 34163033, 2021). "This study, using dedicated-microarrays containing 6864 genes previously known to be involved in cancer, allowed us to select 5 genes (LGALS4, ACS5, CLU, SRI and CCT5) with significant differential expression between tumors and normal tissue." (PMID 19903339, 2009). "Although precise intracellular concentrations are not well defined, proteomic analyses suggest that Sorcin is highly abundant in several tissues and cell types, including cardiomyocytes, neurons, and multidrug-resistant cancer cells, as found in PaxDb." (PMID 41133884, 2025). "Sorcin overexpression increases EMT, migration, and invasion in cancer cells, while sorcin silencing reduces the pool of cancer stem cells (CSCs), decreasing the EMT transition and suppressing metastases via the reduced expression of E-cadherin and VEGF and by the PI3K/Akt axis." (PMID 39199583, 2024). "TRAP1 and Sorcin are co-upregulated in cancer, and this feature is considered a marker of drug resistance, but their reciprocal regulation also relates to TRAP1 translational control of Sorcin; indeed, TRAP1 silencing relates to Sorcin protein instability and degradation." (PMID 33946271, 2021). "Although sorcin is a well-studied protein in the field of calcium cycling, intracellular calcium homeostasis, multidrug resistance, cancer, etc., there exists no article that mentions any signaling axis for its regulation." (PMID 33930463, 2021). "Of course, given the high expression of sorcin in normal tissues (especially heart and brain) and its importance in regulating many important cellular events, targeting sorcin in cancer without undesirable off-target toxicity is not easy." (PMID 32268494, 2020). "Sorcin thus participates in the prevention of ER stress and of the unfolded protein response, and increases escape from apoptosis, shifting the equilibrium between cell life and cell death towards proliferation in MDR cancer cells overexpressing sorcin." (PMID 25197934, 2014). "Interestingly, the genes for sorcin and ABCB1 (the most significant ATP-dependent drug efflux pump) are located near each other on chromosome 7 and can be co-amplified, leading to their simultaneous overexpression in MDR cancer cells." (PMID 39199583, 2024).
cancer (continued). "Sorcin induces gastric tumor cell migration and invasion; sorcin silencing downregulates the expression of cathepsin Z, matrix metalloproteinases 2 and 9 (MMP2 and MMP9), and signal transducer and activator of transcription 3 (STAT3), resulting in the suppression of cancer growth and metastasis." (PMID 32268494, 2020).
tumor (22 papers, 2010 to 2026). "Furthermore, upregulated Sorcin expression was significantly associated with advanced tumor-node-metastasis stage, and higher Sorcin expression was associated with higher pathological grade and clinical stage in HCC patients." (PMID 37833249, 2023). "Spatial transcriptomics localized TMEM176A to fibroblasts and SRI to tumor epithelium, and in vitro SRI knockdown inhibited tumor cell growth, migration and invasion." (PMID 41228276, 2025). "High sorcin expression in hepatocarcinoma cells negatively regulates pyroptosis by interacting with the NLRP3 inflammasome to promote tumor proliferation, migration, and invasion." (PMID 39199583, 2024). "In PDAC tumor tissues from human patients, sorcin was highly expressed in the cytoplasm of PC cells, while p-STAT3, an activated transcription factor, was enriched in the nucleus." (PMID 39516378, 2024). "Sorcin expression was significantly upregulated in tumor tissues compared with adjacent normal tissues (scores of sorcin levels via IHC, PC tissues vs. paired adjacent normal tissues: 6.49 ± 1.68 vs. 2.18 ± 1.02 (n = 88), P < 0.0001)." (PMID 39516378, 2024). "All five PC cell lines we tested (PANC-1, CFPAC-1, BxPC-3, Mia Paca-2, and AsPC-1) recapitulated the elevated expression of sorcin found in patient tumor samples compared with the normal pancreatic duct cell line HPDE6." (PMID 39516378, 2024). "Soluble resistance-related calcium-binding protein (Sorcin) is highly expressed in a variety of tumor cell lines and multidrug-resistant cell lines and participates in the malignant progression of tumors by regulating apoptosis." (PMID 37833249, 2023). "Knockdown Sorcin inhibited epithelial-mesenchymal transitions of tumor cells by regulating the expression of E-cadherin, thereby inhibiting breast cancer cell metastasis." (PMID 37833249, 2023). "Soluble resistance-related calcium-binding protein (Sorcin) is a cytosolic protein prevalent in both normal and tumor cells previously designated V19." (PMID 37833249, 2023). "Sorcin is also highly expressed in tumor cell lines and multidrug-resistant cell lines and is closely associated with the malignancy and poor prognosis of various tumors." (PMID 37833249, 2023). "In the present study, we found that silencing sorcin was related to metastatic activity in tumor cells." (PMID 29262638, 2017). "The results showed that sorcin expression was higher in tumor tissues than that in normal adjacent tissues." (PMID 29262638, 2017). "Sorcin was involved in regulation of myocardial cell excitation–contraction coupling, multi-drug resistance in tumor cells, and cytoprotection." (PMID 28706517, 2017). "Sorcin is overexpressed in several tumor cells as an adaptive mechanism to prevent ER stress and escape apoptosis triggered by chemotherapeutic agents, prompting its further investigation as a novel molecular target to overcome MDR26." (PMID 26577048, 2015). "Overexpression of sorcin has been reported in a number of tumor resistant cell lines." (PMID 40611756, 2025). "Interestingly, we found that sorcin was significantly overexpressed in tumor samples from PDAC patients, especially in PCAND patients." (PMID 39516378, 2024). "As a calcium-binding protein, Sorcin is involved in tumor progression and maintenance of tumor multidrug resistance phenotypes by altering intracellular Ca2+ concentration, affecting signaling transduction, and altering the activity and function of other Ca2+-regulated proteins." (PMID 37833249, 2023). "IHC was utilized to verify whether the expression of sorcin differed between tumor tissues and adjacent normal tissues." (PMID 29262638, 2017). "The overexpression of sorcin has been reported in a number of tumor-resistant cell lines." (PMID 25364401, 2014).
tumor (continued). "Notably, a greater level of sorcin expression was detected in PCAND tumor tissues than in PC + T2DM tumor tissues (sorcin IHC scores, PCAND vs. PC + T2DM: 7.10 ± 1.71 (n = 28) vs. 5.85 ± 1.67 (n = 28), P = 0.008; pure PC vs. PCAND: 6.51 ± 1.51 (n = 32) vs. 7.10 ± 1.71 (n = 28), P = 0.136)." (PMID 39516378, 2024). "In addition, we analyzed EGFR and Sorcin phosphorylation: the average increase of phosphorylation in tumors (phosphorylation in each tumor/phosphorylation in normal surrounding tissue ratio) was obtained for each type of tumor for EGFR and SRI." (PMID 37442828, 2023). "Sorcin (SRI) is a soluble calcium-binding protein frequently overexpressed across diverse malignancies, where it drives tumor progression and mediates multidrug resistance (MDR)." (PMID 41228276, 2025). "Sorcin knockdown decreases the expression of matrix metalloproteinases (MMP2 and MMP9), cathepsin Z, and STAT3, leading to suppressed tumor growth and metastasis." (PMID 39199583, 2024). "Moreover, Sorcin-silenced activates pyroptosis and may change the immunosuppressive environment in which the tumor tissue is located to an immune-activating environment, where immune cells will be continuously recruited to the tumor site." (PMID 37833249, 2023). "Sorcin (SRI), a calcium-binding protein implicated in tumor progression, has not been comprehensively investigated in GBC." (PMID 42041546, 2026). "Sorcin is an important player in angiogenesis, proliferation, EMT and tumor metastasis." (PMID 39199583, 2024). "Interestingly, in rare instances in which the pancreatic tissue section included both the PDAC tumor and the adjacent islets, high sorcin levels in PDAC tumors coincided with low insulin levels and PDX1 levels in tumor-adjacent islets." (PMID 39516378, 2024). "This work, together with other recent papers, shows that Sorcin can be a useful marker of MDR and may represent a therapeutic target for reversing tumor MDR." (PMID 28726784, 2017). "Based on the Western blot results, we performed IHC analysis to study the expression of three proteins, KRT7, KRT19 and SRI, in GSD (non-tumor control), LN negative GBC and LN positive GBC." (PMID 37142981, 2023).
neurodegenerative disease (5 papers, 2014 to 2025). A disorder of the central nervous system characterized by gradual and progressive loss of neural tissue and neurologic function. "The complex and co-operative nature of Sorcin aggregation revealed by stopped-flow light scattering provides a framework for investigating the fundamentals of protein aggregation, a process linked to various neurodegenerative diseases." (PMID 41133884, 2025). "In the present work, we demonstrate that Sorcin is overexpressed in several models of neurodegenerative diseases, ranging from cellular models of PD to murine models of HD, to HD and AD patients." (PMID 33060591, 2020). "Sorcin expression was evaluated in cellular, animal and patient models of neurodegenerative diseases, to evaluate whether it may represent a marker of neurodegeneration, by western blot experiments." (PMID 33060591, 2020). "The present work aims at understanding whether Sorcin expression and function is involved in the rescue of Ca2+ dysregulation and ER stress in neurodegenerative diseases, and whether Sorcin expression results in a pro-survival strategy that helps rescue neurodegeneration-dependent cell damages." (PMID 33060591, 2020). "This study advances our understanding of Sorcin’s function in Ca2+ homeostasis and establishes it as a valuable model system for exploring protein aggregation mechanisms, with potential relevance to MDR and neurodegenerative diseases." (PMID 41133884, 2025).
SRI also shares sentences with these, for which no sentence is quoted: cervical carcinoma (2 papers); colon carcinoma (2); infection (2); lung carcinoma (2); nasopharyngeal carcinoma (2); asthma (1); Ataxia (1); brain cancer (1); cardiac diseases (1); cardiovascular disease (1); colorectal tumours (1); Down syndrome (1); epilepsy (1); gallbladder cancer (1); Hepatic steatosis (1); Insulin resistance (1); Jaundice (1); kidney disease (1); Lewy body diseases (1); liver cancer (1); lymph node metastasis (1); lymphoma (1); multiple myeloma (1); psychosis (1); respiratory diseases (1); Ventricular arrhythmia (1).